DRD1 (dopamine receptor D1)
Diseases named in the same sentence as DRD1 in open-access papers (continued):
Sharing a sentence is not in itself a finding about the gene and the disease.
cancer (19 papers, 2016 to 2025). A tumor composed of atypical neoplastic, often pleomorphic cells that invade other tissues. "Collectively, our data point toward a poor prognostic role for loss of DRD1 expression and increased DRD1 methylation in cancer." (PMID 38572507, 2024). "DRD1 is a member of the dopamine receptor family, has been implicated in cancer progression." (PMID 38899930, 2024). "An increasing number of researchers have elucidated that DRD1 is a key player in several cancers and a potential valid therapeutic target for certain receptors in cancer therapies." (PMID 34717619, 2021). "By applying an online database, we demonstrated that DRD1 expression is significantly decreased across cancers at the transcriptional level." (PMID 34717619, 2021). "In this study, we evaluated the correlations between DRD1 expression in various cancers and immune cell infiltration/immune purity." (PMID 34717619, 2021). "Dopamine and dopamine receptor D1 (DRD1) are reported to be involved in the progression of various cancers." (PMID 34717619, 2021). "A77636 inhibited migration of cancer cells in a DRD1-dependent fashion and suppressed development of bone-resorbing osteoclasts by downregulating NFATc1 through the elevation of phosphorylation of eIF2α." (PMID 28374823, 2017). "Whether DRD1 induces nuclear translocation of PD‐L1 in cancer cells and induces any downstream signaling effects is an intriguing future direction for DRD1 signaling research." (PMID 38572507, 2024). "The results from the present study indicate that the efficacy of mechanical loading and FP in cancer cells may depend on the expression levels of DRD1 and DRD2." (PMID 34031366, 2021). "In addition, DRD1 expression has a significant correlation with macrophage, T cell and B cell infiltration, indicating that DRD1 expression might be involved in shaping the cancer immune microenvironment in HCC." (PMID 34717619, 2021). "In conclusion, 5-HTR1B, 5-HTR2B, DRD1, and DRD2 show mRNA overexpression in a broad spectrum of common and rare cancers." (PMID 31478179, 2020). "For example, our data demonstrate that miR-21 and miR-155 are related with progression and invasion of GBM by regulating marker genes of cancer metastasis, such as LHX6, DRD1, NEUROG1 and RAB27B, and thereby contributing to GBM patient survival." (PMID 29312626, 2017). "Constitutive activation of dopamine receptors DRD1, DRD2, DRD5 has been reported in relation to development and neurological disease, but the impact of the functional change on cancer progression and metastasis remains unclear." (PMID 39679842, 2025). "Their expression levels are likely to regulate the expression of other genes in this HCC network, but as a dopamine receptor gene, there is no clear evidence that DRD1 is related to cancer." (PMID 34212175, 2021). "Results showed that expressions of DRD1, GABRA3, SLC6A3, GABRQ, and SCN4A in cancer were significantly higher than those in noncancer tissues." (PMID 35401884, 2022).
psychiatric disorder (17 papers, 2014 to 2024). A disorder characterized by behavioral and/or psychological abnormalities, often accompanied by physical symptoms. "However, only one female-biased psychiatric disorder adverse event was associated with a drug that targets DRD1." (PMID 38167211, 2024). "Alterations in DRD1 density are associated with cognitive dysfunction in psychiatric disorders, and in the PFC DRD1 also plays a key role in the regulation of working memory." (PMID 36059987, 2022). "We further measured the mRNA levels of a number of genes known to be involved in the pathology of psychiatric disorders, including Bdnf, Fosb, Drd1/2, Grik2, Hdac1/9v, and Grin2a/b." (PMID 36582489, 2022). "In comparison to these well-established associations, the connection of psychiatric disorders and behavioral traits with other DR genes are much less consistent, although there are some GWA studies showing that DRD1 is associated with educational attainment and DRD3 with neuroticism." (PMID 39619336, 2024). "PET studies using radioligands for DRD1 have shown some promise as a means of researching the DA system in psychiatric diseases, ideally with higher selectivity radioligands, so that DRD1 can be evaluated as a candidate biomarker for disease and ultimately for treatment." (PMID 36059987, 2022). "Firstly, in both the Caucasian samples with and without a history of mental illness, sociosexual orientation was found to be significantly related to variation in dopamine DRD1 rs265981 and oxytocin OXTR rs237887." (PMID 30393594, 2018).
neurological disorders (9 papers, 2011 to 2025). "Another gene upregulated in the temporal lobe which has been linked to neurological disorders is the Dopamine Receptor D1 gene (DRD1)." (PMID 38045237, 2023). "At present, research reports on DRD1 have focused mainly on human pathological phenomena, using mice as models to study neural signal transmission, hormone secretion, growth and development, and neurological disorders involving the DRD1 gene in the brain." (PMID 40149425, 2025). "The mRNAs of Rgs9, Gpr88, Drd2, Sh3rf2, Tac1, Serpina 9, Rxrg, Drd1, Rasgrp2, Six3, Gpr6, Pdyn, Gng7, and Pde1b were all upregulated (p < 0.05); all of these have been reported to be more or less related to nervous system diseases." (PMID 33819195, 2021).
infection (8 papers, 2016 to 2025). The state of being infected such as from the introduction of a foreign agent such as serum, vaccine, antigenic substance or organism. "The infection with AAV1 encoding the miR-382-3p or miR-674-3p sponge significantly reduced the levels of respective miRNAs and increased the expression of the Drd1 transcript in the LV wall of WT mice." (PMID 32060266, 2020). "Next, FLEX-shFyn was packaged into a lentivirus (Ltv-FLEX-shFyn) and the efficacy of in vivo infection in D1R DMS neurons was evaluated by using Drd1-Cre-Ai14 mice which express Cre recombinase and the red fluorescence protein, tdTomato specifically in D1R neurons." (PMID 28912680, 2017).
DRD1 also shares sentences with these, for which no sentence is quoted: Parkinsonism (8 papers); movement disorder (6); Dystonia (5); essential hypertension (5); bipolar disorder (4); Tics (4); Alcoholism (3); ovarian carcinoma (3); amnesia (2); anxiety disorder (2); Arrhythmia (2); bone cancer (2); brain disorder (2); cardiac arrhythmia (2); cognitive decline (2); colitis (2); encephalitis (2); epidermoid carcinoma (2); Hyperammonemia (2); ischemic stroke (2); metabolic disorders (2); migraine (2); myopia (2); neurodegenerative disease (2); osteoporosis (2); osteosarcoma (2); acute kidney injury (1); acute myeloid leukemia (1); adenocarcinoma (1); aspiration pneumonia (1).
A further 58 diseases each share a sentence with DRD1 in 1 paper.